BRCA1 (BRCA1 DNA repair associated)
Diseases named in the same sentence as BRCA1 in open-access papers (continued):
Sharing a sentence is not in itself a finding about the gene and the disease.
hematological malignancies (7 papers, 2019 to 2025). "Studies have identified that HL survivors carrying BRCA1/2 mutations face a significantly heightened risk of developing secondary hematologic malignancies (SHM) and should therefore receive early intervention." (PMID 40406264, 2025).
digestive system cancer (6 papers, 2014 to 2024). A primary or metastatic malignant neoplasm involving any part of the digestive system. "In another study, high expression of BRCA1 cytoplasmic expression was associated with favorable OS in digestive system cancers." (PMID 30479693, 2018).
metabolic disorders (5 papers, 2015 to 2025). "For example, identifying a BRCA1 mutation in a child undergoing rWGS for a metabolic disorder raises questions about whether to disclose this information, especially when it has implications for adult-onset conditions." (PMID 41404425, 2025). "This phenomenon was detected in oncogenetics (BRCA1/2 testing), inborn metabolic disease genotyping (FAH testing), hematology research etc." (PMID 33633783, 2021). "It underscores the significance of the BRCA1-mediated PI3K/Akt signaling pathway in the development and progression of metabolic disorders." (PMID 40138287, 2025). "Our findings shed light on the complicated processes of metabolic control and emphasize the function of the BRCA1-mediated PI3K/AKT signaling pathway in the etiology and progression of metabolic disorders." (PMID 40138287, 2025).
neurological diseases (5 papers, 2015 to 2024). "The BRCA1 gene plays a vital role in DNA repair and cellular responses to DNA damage, with associations to senescence and various neurological disorders." (PMID 39126055, 2024).
hematologic cancers (4 papers, 2007 to 2025). "Meta-analyses of statistical information compared risks for hematologic cancers vs. mutations for the components in a model pathway containing BRCA1/2 gene products." (PMID 17683622, 2007). "Independent and unrelated lines of investigation strongly implicate BRCA1 and BRCA2 deficiencies in hematologic cancers." (PMID 17683622, 2007). "Non-functional mutations of BRCA1 which discovered in hematopoietic cancer also disturbed normal differentiation." (PMID 32826945, 2020).
autosomal dominant disease (2 papers, 2011 to 2021). Autosomal dominant form of disease. "HBOC is an autosomal-dominant disease that is diagnosed based on the presence of BRCA1 or BRCA2 (BRCA1/2) pathogenic germline mutations." (PMID 33544084, 2021).
blood cancers (2 papers, 2023 to 2025). "To date, one G4 ligand in ongoing human clinical trials, CX-5461, has been reported to successfully treat blood cancers and BRCA1/2-deficient tumors." (PMID 40833407, 2025).
head and neck tumors (2 papers, 2008 to 2024). "Another study confirmed that HPV+ head and neck tumors have higher expression of DNA repair genes across all DDR pathways, including higher BRCA1 and Rad51 protein levels than HPV- head and neck tumors." (PMID 38730612, 2024).
mental illness (1 paper, 2024). "This led to additional pilot funding from the Irving Institute and the Basser Center to expand work on use of the decision aid among Orthodox Jewish women eligible for BRCA1/2 testing and evaluate mental illness as a barrier to genetic testing." (PMID 39345700, 2024).
reproductive diseases (1 paper, 2024). "Both BRCA1 and BRCA2 proteins are commonly mutated in female reproductive cancers, so it is likely that there is a connection to their possible mutation in reproductive diseases." (PMID 39359934, 2024). "Both BRCA1 and BRCA22 as well as proteins comprising the BCDX2 and CX3 complexes are present on breast cancer screening panels, but their roles in reproductive diseases remain less mechanistically defined." (PMID 39359934, 2024).
reproductive tumors (1 paper, 2020). "Mutations of BRCA1 genes are associated with increased reproductive tumors in humans mutations that may predispose animals to reproductive neoplasms have not been investigated in felids other than jaguars." (PMID 33322396, 2020).
BRCA1 also shares sentences with these, for which no sentence is quoted: neurofibromatosis type 1 (8 papers); benign breast disease (7); Hereditary Pancreatitis (7); familial colorectal cancer (6); hereditary diffuse gastric cancer (6); Peutz-Jeghers syndrome (6); bile duct cancer (5); breast disease (5); ischemic heart disease (5); chordoma (4); endothelial dysfunction (4); Hyperinsulinemia (4); premature ovarian failure (4); Adrenocortical carcinomas (3); atypical ductal hyperplasia (3); chronic obstructive pulmonary disease (3); familial prostate cancer (3); Hodgkin’s disease (3); Klinefelter syndrome (3); osteoporosis (3); Pancreatic cysts (3); small bowel carcinomas (3); uterine sarcoma (3); xeroderma pigmentosum (3); acinic cell carcinoma of the breast (2); allergies (2); Ascites (2); bladder urothelial carcinoma (2); bone marrow failure syndrome (2); breast carcinoma in situ (2).
A further 241 diseases each share a sentence with BRCA1 in 2 papers or fewer.